CITED1 (Cbp/p300 interacting transactivator with ED-rich tail 1)
Diseases named in the same sentence as CITED1 in open-access papers (continued):
Sharing a sentence is not in itself a finding about the gene and the disease.
fungal infection (1 paper, 2020). "This raises the interesting possibility that Cited1 may serve a similar function during fungal infection." (PMID 32857777, 2020).
hepatoblastoma (1 paper, 2014). Hepatoblastoma (HB) is a malignant hepatic tumor and is the most common pediatric liver cancer. "We have shown previously that CITED1 repressed epithelial differentiation of cultured metanephric mesenchymes, and induced the WNT inhibitor KREMEN1, the DKK1 receptor, in a hepatoblastoma cell line." (PMID 24481423, 2014).
hypothyroidism (1 paper, 2011). Abnormally low levels of thyroid hormone. "Notably, expression pattern of four out of five genes affected by hypothyroidism (Angpt1, CD55, Cited1, and Mdk) was reversed by T3 treatment of hypothyroid animals, (p<0.05)." (PMID 21966411, 2011).
lymphoma (1 paper, 2017). A malignant (clonal) proliferation of B- lymphocytes or T- lymphocytes which involves the lymph nodes, bone marrow and/or extranodal sites. "This identified upregulation of TGFβ signalling as the most affected molecular pathway in Eμ-Myc;shBcor lymphomas (Bonferroni corrected P=0.0058), with enhanced expression of TGFβ pathway members (Cited1, Bambi, Acvr2b, Smad3, Mapk12, Tgfb2)." (PMID 28262675, 2017).
odontogenic cyst (1 paper, 2024). A cyst in the jaw that arises from tissues of tooth development. "Considering their developmental and inflammatory origin, this study aimed to investigate the potential association between the expression of CITED1 in odontogenic cysts with different origins." (PMID 38997708, 2024). "Further investigations are needed to elucidate the exact mechanisms underlying the differential expression of CITED1 and its implications for the development and progression of odontogenic cysts." (PMID 38997708, 2024). "Overall, incorporating the expression patterns of CITED1 into clinical practice may enhance diagnostic accuracy, guide treatment decisions, and improve prognostic assessments for patients with odontogenic cysts." (PMID 38997708, 2024). "Clinically, CITED1 expression levels could complement traditional diagnostic methods and contribute to a more comprehensive assessment of odontogenic cysts." (PMID 38997708, 2024). "Positive CITED1 expression in all three types of odontogenic cysts suggest a potential role for CITED1 in the pathogenesis of odontogenic cysts, particularly in keratocysts." (PMID 38997708, 2024). "Furthermore, the expression of CITED1 was found to be higher in radicular cysts compared to dentigerous cysts, suggesting differential regulatory mechanisms among various types of odontogenic cysts." (PMID 38997708, 2024). "However, further research is needed to validate these findings and explore the therapeutic implications of targeting CITED1 in odontogenic cyst management." (PMID 38997708, 2024). "In this study, CITED1 expression was found all odontogenic cysts, but was highest in keratocysts." (PMID 38997708, 2024). "It is evident that CITED1 expression was detected in all types of odontogenic cysts studied." (PMID 38997708, 2024). "This study investigated expression of CITED1 protein in different types of odontogenic cysts." (PMID 38997708, 2024). "Consistent with literature, CITED1 could be potentially a molecular marker for odontogenic cysts." (PMID 38997708, 2024).
odontogenic keratocysts (1 paper, 2024). "Radicular cysts had significantly lower nuclear and cytoplasmic CITED1 expression than in odontogenic keratocysts." (PMID 38997708, 2024). "Nuclear and cytoplasmic CITED1 expression was significantly higher in odontogenic keratocysts than in radicular and dentigerous cysts." (PMID 38997708, 2024). "CITED1 immunoexpression was highest in odontogenic keratocysts, followed by radicular cysts, and lowest in dentigerous cysts." (PMID 38997708, 2024). "Nuclear and cytoplasmic CITED1 expression was significantly elevated in odontogenic keratocysts compared to radicular and dentigerous cysts." (PMID 38997708, 2024). "Dentigerous cysts significantly had the lowest nuclear and cytoplasmic CITED1 expression compared to odontogenic keratocysts and radicular cysts." (PMID 38997708, 2024). "CITED1 expression (signal) was the highest in odontogenic keratocyst, secondly in radicular cyst and the lowest in dentigerous cyst." (PMID 38997708, 2024).
radicular cyst (1 paper, 2024). "Our findings showed there were differential expression of CITED1 among keratocysts, radicular cysts, and dentigerous cysts." (PMID 38997708, 2024). "Expression of CITED1 was higher in radicular cysts than in that of dentigerous cyst." (PMID 38997708, 2024).
sarcoma (1 paper, 2008). A usually aggressive malignant neoplasm of the soft tissue or bone. "Among the other putative gene targets, CITED1, which is a major discriminator of human ESFT with respect to other sarcomas was strongly induced by the fusion proteins but only weakly by the DBDM." (PMID 18648544, 2008).
teratoma (1 paper, 2018). A non-seminomatous germ cell tumor characterized by the presence of various tissues which correspond to the different germinal layers (endoderm, mesoderm, and ectoderm). "To test the differentiation potential of Cited1-transfected cells in vivo, we injected the cells subcutaneously into NOD/SCID mice for teratoma formation." (PMID 30206204, 2018).
trophoblastic tumors (1 paper, 2018). "In contrast, overexpression of Cited1 in ESCs induces a trophoblast-like state with elevated expression of trophoblast marker genes in vitro and generation of trophoblastic tumors in vivo." (PMID 30206204, 2018). "In contrast, ectopic Cited1 expression induces ESC trans-differentiation into trophoblast-like cells under the self-renewal culture condition and trophoblastic tumors with internal hemorrhage in vivo." (PMID 30206204, 2018).
tumours (14 papers, 2012 to 2025). "Conversely, work from Alan Clarke’s lab demonstrated that ApcMin mice deficient for the Wnt target gene Cited1 developed significantly less tumours and had extended life span compared to their ApcMin, Cited1 proficient littermates." (PMID 27196929, 2016). "We crossed Cited1 null mice with ApcMin/+ and AhCre+Apcfl/fl mice and determined the impact of Cited1 deficiency on tumour growth/initiation including tumour multiplicity, cell proliferation, apoptosis and the transcriptome." (PMID 23935526, 2013). "We show that Cited1 is up-regulated in both human and murine tumours, and that constitutive deficiency of Cited1 increases survival in ApcMin/+ mice from 230.5 to 515 days." (PMID 23935526, 2013). "Moreover, the association with the luminal subtype was retained in tumours, and our previous observation that CITED1 expression correlated with ERα-positivity was confirmed." (PMID 37322548, 2023). "In WT, nephrogenic progenitor cells co-expressing SIX2 and CITED1 have been identified as tumor-initiating cells, capable of recapitulating tumorigenesis in xenotransplantation models." (PMID 40534868, 2025). "While SIX2+CITED1+ WT progenitor cells have been demonstrated to drive tumor initiation, the molecular triggers enabling their survival and immune evasion within the immunocompetent microenvironment of WT remain elusive." (PMID 40534868, 2025). "CITED1 mRNA is associated with estrogen-receptor positivity and selectively expressed in the GOBO dataset of cell lines and tumours representing the luminal-molecular subtype." (PMID 37322548, 2023). "To investigate the biological effect of CITED1 silencing on tumor growth in vivo, we proceeded with the establishment of a subcutaneous xenograft tumor model in nude mice." (PMID 30450190, 2018). "The growth curve revealed a dramatic decrease in tumor growth in the group in which CITED1 was knocked down." (PMID 30450190, 2018). "We found a correlation between rounded cell morphology and higher CITED1 levels in vivo, both of which correlated with distance from the core of the tumor." (PMID 26526369, 2015). "The overlap between the primary tumour classifying and cell line classifying systems allows us to infer that CITED1 expression is most likely restricted to a subset of MITF high ‘pigmentation’ subtype tumours." (PMID 25755924, 2015). "Mechanistically, we have shown that mutation of the transcriptionally active carboxy terminus of CITED1 perturbs in a dominant-negative manner embryonal tumor cell proliferation in vitro and tumorigenesis in a xenograft model." (PMID 24481423, 2014). "Our data is consistent with another version of this “just right” concept where perturbation of Cited1 leads to increased dephosphorylated β-catenin and hyper-activation of the Wnt pathway to a level that is incompatible with maximum tumour growth." (PMID 23935526, 2013). "Integration of scRNA‐seq data (GSE175698) showed distinct differences in gene expression between SIX2+CITED1+ cells from hFK and WT, WT xenografts and the tumor of origin (WT‐TOT); similarities between WT SIX2+CITED1+ cells and their tumor of origin (WT‐TOT) are evident." (PMID 37114795, 2023). "Moreover, the tumor size and weight of the group in which CITED1 was silenced were lower than the tumor size and weight of the control group." (PMID 30450190, 2018). "CITED1 seems to confer a metastatic advantage by promoting escape from the primary niche, migration, invasion, attachment to vessels, successful colonization, and tumor outgrowth." (PMID 26526369, 2015). "In order to understand whether this early regulation of lung colonization could eventually lead to successful tumor outgrowth over time, we generated stable cell lines with reduced levels of CITED1 using two different small hairpin RNAs (shRNAs)." (PMID 26526369, 2015). "Detection of high levels of Cited1/CITED1 expression in both human and murine tumours suggests that Cited1/CITED1 may play a role in intestinal tumourigenesis." (PMID 23935526, 2013).
tumours (continued). "Previous studies have identified SIX2+CITED1+, PROM1+ or NCAM1+ALDH1+ tumor cells as potential CSC-like populations in WT." (PMID 40098972, 2025). "The results revealed that tumor cells exhibited significantly elevated expression levels of WT1, SIX1, SIX2, and CITED1, supporting the accurate annotation of tumor cells." (PMID 40534868, 2025). "One seemingly paradoxical observation from our study and previous investigations is that although CITED1 behaves as a negative regulator of MITF, both their expression levels appear positively correlated across cells lines and tumours." (PMID 25755924, 2015). "In a human WT cell line, we now show that forced expression of wild-type CITED1 imparts a multi-level inhibition of the WNT pathway, appearing collectively and logically to maintain the stem state for this embryonal tumor." (PMID 24481423, 2014). "scRNA‐seq data revealed a strong overlap between the tumor of origin and the SIX2+CITED1+ cells." (PMID 37114795, 2023). "To decipher the renal commitment signature of the SIX2+CITED1+ cells, we perform trajectory analysis on the SIX2+CITED1+ cells together with the tumor from which they were originally selected (WT total, WT‐TOT) and the xenograft that they generated in vivo, identifying 3 distinct states." (PMID 37114795, 2023). "Tumour oncogenes include SPP-1, MITF, CITED-1, GDF-15, c-Met, and HOX loci." (PMID 23091727, 2012). "CITED1 expression was elevated in tumor tissues compared with corresponding noncancerous tissues." (PMID 30450190, 2018).
cancer (9 papers, 2013 to 2024). A tumor composed of atypical neoplastic, often pleomorphic cells that invade other tissues. "Our pathway analysis demonstrated that the core molecular targets of CITED1 were significantly associated with thyroid hormone, endocrine resistance, estrogen, and cancer-related signaling pathways." (PMID 38997708, 2024). "CITED1 deregulation is associated with a variety of cancers." (PMID 26526369, 2015). "The top five targets of CITED1 were identified, primarily showing enrichment in hormone and cancer related pathways." (PMID 38997708, 2024). "Cells expressing SIX2 and CITED1 fulfill cancer stem cell criteria by reliably recapitulating WT in transplantation studies." (PMID 37114795, 2023). "On the other hand, the SMAD adaptor CITED1 was originally described to play a role in melanocyte pigmentation and has been described to be upregulated in some cancers." (PMID 26526369, 2015). "Second, PTGS2 (prostaglandin-endoperoxide synthase 2; protein product is COX2) was significantly upregulated in CITED1-expressing WiT49 cells on the gene expression microarray and was then validated on the real-time PCR cancer drug target array." (PMID 24481423, 2014). "Its relevance to carcinogenesis has already been described as Cited1 up-regulation has been observed in various cancers." (PMID 23935526, 2013). "We demonstrated that SIX2+CITED1+ cells from WT exhibited nephrogenic cancer stem cell (CSC) traits and, upon transplantation into NOD/SCID mice, formed consecutive xenografts with histological features similar to the WT of origin, as well as metastatic capabilities." (PMID 37114795, 2023). "Interestingly, real time PCR screening of 84 cancer drug targets uncovered two genes that appeared significantly upregulated in response to CITED1 ectopic expression in a human WT cell line." (PMID 24481423, 2014). "CITED1 modification of WNT signaling may reveal targets to induce WT cancer stem cell differentiation and to repress β-catenin-driven oncogenicity." (PMID 24481423, 2014). "Notably, accumulating evidence has shown that CITED1 plays critical roles in cancer pathogenesis." (PMID 30450190, 2018). "Given the emerging theory from these studies, that CITED1 imparts a cancer stem cell phenotype to WT blastema having concomitant deregulation of cellular growth control, we supposed this model system could reveal opportunities to identify new and unique targets for therapeutic intervention." (PMID 24481423, 2014). "Those in vivo studies that have been performed have instead focused on the impact of Cited1 gene deletion or the effect of CITED1 mutants on development and cancer rather than its role in myeloid cells." (PMID 38646545, 2024).
infection (2 papers, 2010 to 2020). The state of being infected such as from the introduction of a foreign agent such as serum, vaccine, antigenic substance or organism. "As all previous experiments were performed using a relatively high concentration of Cn (MOI 3:1) with cells harvested at 24 h post-infection, a final experiment was performed to determine whether Cited1 was induced at lower Cn concentrations and earlier timepoints." (PMID 32857777, 2020).
colorectal (1 paper, 2013). "This process is accompanied by multiple changes in gene expression, including upregulation of Cited1, whose role in colorectal carcinogenesis is unknown." (PMID 23935526, 2013).
retinal disorder (1 paper, 2020). Any disease or disorder of the retina. "In this light, the combination of CITED1 and PDE6B mutations could lead to the development of retinal disorders, explaining both the absence of disease-phenotype in hemizygous controls and the intrafamilial variability." (PMID 33302505, 2020).
CITED1 also shares sentences with these, for which no sentence is quoted: thyroid (3 papers); thyroid tumor (2); Autoimmunity (1); basal cell carcinoma (1); metastatic melanoma (1); papillary carcinoma (1); polyp (1); spina bifida (1).